TRAV11 (T cell receptor alpha variable 11 (pseudogene))
Synonyms: TCRAV11S1
Gene: T-cell receptor variable (V) pseudogene on chromosome 14 (21,829,539 to 21,830,070, forward strand). Ensembl gene ENSG00000256474.
Diseases named in the same sentence as TRAV11 in open-access papers:
TRAV11 is named in the same sentence as 1 disease in open-access papers, as found by Europe PMC text mining. Sharing a sentence is not in itself a finding about the gene and the disease.
TRAV11 shares sentences with these, for which no sentence is quoted: COVID-19 (1 paper).